BMPR2 (bone morphogenetic protein receptor type 2)
Diseases named in the same sentence as BMPR2 in open-access papers (continued):
Sharing a sentence is not in itself a finding about the gene and the disease.
tumor (52 papers, 2009 to 2025). "Loss-of-function mutations or the decreased expression of BMPR2 are linked to heightened tumor proliferation, infiltration, and spread to other parts of the body." (PMID 40136410, 2025). "BMPR2, essential for vascular homeostasis, is also implicated in tumor suppression and modulation of the tumor microenvironment." (PMID 40923964, 2025). "It was found that translation-controlled tumor proteins were highly expressed in exosomes released by blood-grown endothelial cells with BMPR-2 mutations, which was associated with heritable PH." (PMID 36419957, 2022). "It appears to have an overall oncogenetic effect, by activating more tumor-causing than tumor suppressing pathways, possibly through the increase in BMPR2 gene expression." (PMID 25901570, 2015). "In contrast, our patients developed these neoplasms at markedly younger ages (34, 47, and 54 years), supporting the hypothesis of a potential cancer predisposition in patients with alterations in the BMPR2 pathway." (PMID 40923964, 2025). "In murine models, fibroblast-specific deletion of BMPR2 significantly increases pulmonary metastasis, associated with higher levels of proinflammatory cytokines and infiltration by myeloid cells that promote a prometastatic tumor microenvironment." (PMID 40923964, 2025). "Loss of miR-100-3p promoted tumor growth and BMPR2 expression." (PMID 31889906, 2019). "The inhibition of BMPR2 resulted in enhanced tumor cell proliferation, motility, and invasion, as well as the development of a more inflammatory tumor microenvironment." (PMID 40136410, 2025). "Collectively, these findings underscore the relevance of BMPR2 not only in vascular regulation but also as a modulator of the tumor microenvironment and cancer progression." (PMID 40923964, 2025). "This phenomenon does not correlate with increased primary tumor growth, but rather with enhanced dissemination and immune evasion, suggesting BMPR2 acts as a negative regulator of stromal inflammation, limiting tumor progression." (PMID 40923964, 2025). "The results demonstrated that SKP1 was highly expressed in tumour tissues, whereas Smad2 and BMPR2 were inhibited, which was consistent with the findings of scRNA‐seq data." (PMID 39548559, 2024). "At the same time, the apoptosis-related gene PIM1, proliferation-related gene CCND1, migration- and invasion-related gene BMPR2, and tumor immunocyte infiltration-related gene IFNAR1 also appeared in the core network." (PMID 35241097, 2022). "As a vital component of BMP signal transduction, BMPR2 plays an important role in the tumorigenesis and development of cancer by acting as a tumor promoter (upregulation) or tumor suppressor (downregulation)." (PMID 35570745, 2022). "We compared LAC tissues with adjacent normal tissues and found that in tumor tissues, the expression levels of circ_0129047 and BMPR2 were decreased, while those of miR‐1206 were elevated." (PMID 35570745, 2022). "This was in contrast to the NPC cell line, C666-1, and authentic NPC tumours, where BMPR2 expression was maintained." (PMID 32708289, 2020). "miR-100-3p acted as a tumor-suppressor miRNA that down-regulated BMPR2, which consequently inhibited the ERK/AKT signaling and activated Bax/Bcl2/Caspase3 signaling." (PMID 31889906, 2019). "Over-expression of miR-100-3p simultaneously inhibited tumor growth and down-regulated BMPR2 expression." (PMID 31889906, 2019). "In summary, we identified, for the first time, that the tumor suppressor miRNA miR-100-3p directly targeted to BMPR2 and consequently regulated the ERK/AKT and Bax/Bcl2-Caspase3 signaling pathways in GC." (PMID 31889906, 2019). "BMPR2 suppression increased tumor cell proliferation, migration, and invasion in addition to creating a more inflammatory tumor microenvironment." (PMID 30149506, 2018). "As an important component of BMP signal transduction, BMPR2 plays a pivotal role in tumor development." (PMID 28938584, 2017).
tumor (continued). "Genes such as GATA4, CLDN23, MICB, MFHAS1, and BMPR2 were enriched in multiple signatures including estrogen response, coagulation, DNA repair, tumor-promoting inflammation, immune evasion, angiogenesis, sustained proliferative signaling, resistance to cell death, and metastasis." (PMID 40863222, 2025). "Conversely, in vitro functional studies have demonstrated that BMPR2 may exert pro-oncogenic effects in certain cellular contexts, enhancing tumor cell proliferation and migration." (PMID 40923964, 2025). "Furthermore, we found co-mutation with MSH3 across the tumours underlying each model, ranging from 20% (SRCAP) to 33% (BMPR2) of the mutated tumours." (PMID 36883553, 2023). "In CRC lacking SMAD4, BMPR2 can bind to LIM domain kinase 1 to activate the Rho/Rho-associated protein kinase (ROCK) pathway to promote tumor invasion and metastases." (PMID 35805024, 2022). "In GEPIA database, both ADARB1 and BMPR2 were downregulated in tumor samples." (PMID 35570745, 2022). "This can occur through a variety of mechanisms, which may involve a loss-of-function mutation or epigenetic silencing of BMPR2, or through paracrine induction of BMP antagonists such as Gremlin on tumour-associated stromal cells." (PMID 32708289, 2020). "Moreover, in tumor cells with miR-100-3p inhibition, more ki67 and BMPR2 positive cells were observed." (PMID 31889906, 2019). "In some tumors, BMPR2 plays a role as a tumor suppressor gene." (PMID 28938584, 2017). "The role of BMPR2 remains unclear and reports suggest that this protein can also have tumour-suppressing and -promoting roles within different cells." (PMID 26437339, 2015). "In vivo tumorigenicity assay in mice indicated that inhibition of BMPR2 reduced tumor growth." (PMID 25501832, 2014). "A total of 50.0% of tumor samples were positive for BMPR2 staining." (PMID 25501832, 2014). "Risk factors, like STC1, COL5A2, COL3A1, and BGN, were significantly correlated with poor OS, while BMPR2 and PGLYRP1 were only found to be protective factors in 2 of 33 tumor types." (PMID 36479101, 2022). "BMPR2 is directly involved in BMP branch signal transduction in the TGF-β/BMP-pathway and has been reported to play a dual role in regulating tumor growth." (PMID 35805024, 2022). "In conclusion, circ _0129047 was found to play a tumor suppressive role in LAC progression; it upregulated BMPR2 expression to inhibit LAC progression by sponging miR-1206." (PMID 35570745, 2022). "To evaluate the effect of both compounds on genes/proteins previously demonstrated to be important in the tumor–macrophage interaction, we also evaluated the gene expression of CD274 (Pdcd1, PD-L1), TLR4, BMPR2 and miR-21 by RT-qPCR on the treated cell lines." (PMID 35053451, 2022). "Surprisingly, in our tumor series, miR-23a-3p expression was inversely correlated with ELK1 and CXCL8 expression and positively correlated with BMPR2 expression." (PMID 33800656, 2021). "Since previous studies using GBM-TICs have shown tumor-to-tumor variation in the expression of BMP receptors, we first determined the mRNA levels of BMP7, BMPR1A, BMPR1B and BMPR2 genes by real-time qRT-PCR in our primary cell lines." (PMID 25860932, 2015). "The finding that overexpression of ZNF191 significantly down-regulated BMPR2, PDGFR and MYO6, whereas silencing of ZNF191 increased BMPR2, PDGFR and MYO6 expression suggests a tumor suppressor role for ZNF191 in human cancers." (PMID 19463170, 2009). "Integration of all these data unveiled that the BMP-responsive (i.e. High PROGENy TGF-β/BMP score) pool of tumor cells correlates significantly with BMP receptors expression, in particular to BMPR2, BMPR1B, BMPR1A, and ACVR1 levels, respectively in 8, 5, 5, and 4 out of 10 samples." (PMID 39373720, 2024). "The probability of interaction between tumor cells and fibroblast receptor-ligand pairs was higher than that of thyroid cells, especially in TGFB1/ACVR1/TGFBR1, FGF18/FGFR1, BTC/EGFR, BMP8A/BMPR1A/BMPR2, and BMP8A/BMPR1A/BMPR2." (PMID 37733241, 2023).
tumor (continued). "We first sought to examine the expression levels of BMPR2, BMPR1A and BMPR1B in NB tumour samples." (PMID 32714600, 2020). "Along with our data, all of these findings suggest that reduced expression of BMPR1B and BMPR2, and/or increased expression of BMPR1A, may play a role in the determination of a proliferative cell fate, at least in some types of tumours." (PMID 32714600, 2020). "Other novel tumor suppressor genes identified here include KANSL1, a scaffold protein for histone acetylation complexes, BMPR2, a receptor serine/threonine kinase for bone morphogenetic proteins, MAP2K7, involved in MAP-kinase signaling, and NIPBL, a member of the cohesin complex." (PMID 29056346, 2017). "In general, BMPR2 silenced 143B cells inhibited in vivo metastasis, but not primary tumor growth." (PMID 28938584, 2017). "However, there were no obvious differences between BMPR2 expression and gender, age, tumor location, and histological types." (PMID 28938584, 2017).
cancer (45 papers, 2009 to 2025). A tumor composed of atypical neoplastic, often pleomorphic cells that invade other tissues. "The decreased expression of BMPR2 demonstrated a statistically significant association with unfavorable prognosis, including cancer recurrence and lower 5-year survival rates." (PMID 40136410, 2025). "From the Cancer Hallmarks perspective, genes such as BMPR2, MICB, CLDN23, and WNT4 were linked to critical processes such as Replicative immortality, resistance to cell death, evading immune destruction, and angiogenesis." (PMID 40863222, 2025). "Previous research suggested three genes, Speckle-Type BTB/POZ Protein-Like (SPOPL), Mitogen-Activated Protein Kinase 1 (MAPK1), and Bone Morphogenetic Protein Receptor Type 2 (BMPR2) were associated with stemness in cancers." (PMID 36769824, 2023). "Accumulating research has revealed that aberrant expression of BMPR2 is implicated with many cancers." (PMID 28938584, 2017). "BMPR2 mutations may predispose to early onset epithelial cancers, warranting investigation into cancer risk and screening strategies in this population." (PMID 40923964, 2025). "This intersection between vascular signaling and carcinogenesis raises new hypotheses regarding cancer risk in BMPR2 mutation carriers." (PMID 40923964, 2025). "BMPs, cytokines that control the function of many types of cells, exert their role through BMPR1A, BMPR1B, and BMPR2 class receptors with many other receptors in each class, and loss of function can be associated with muscular-skeletal and, cardiovascular diseases, cancer, or CP." (PMID 37238140, 2023). "Further research is necessary to gain a thorough understanding of the processes and therapeutic implications of BMPR2 in cancer." (PMID 40136410, 2025). "This review investigates the significance of BMP receptor signaling, BMPR2, and its dual involvement as a promoter and as an inhibitory function in various cancers, vascular development, and osteogenesis." (PMID 40136410, 2025). "Joel Kaye research has indicated that the act of suppressing BMPR2 leads to a higher rate of cell death in cancer cells compared to inhibiting BMP type 1 receptors." (PMID 40136410, 2025). "The precise function of BMPR2 can differ based on the particular type of cancer and the cellular environment." (PMID 40136410, 2025). "An improvement in mitochondrial bioenergetics was shown not only in cancer cells but also in normal mouse hippocampal neurons and in C. elegans, suggesting that the regulation of energy homeostasis by BMPR2 is conserved." (PMID 39315260, 2024). "For example, TGFβ–BMP signalling was mostly inactivated by co-SMAD SMAD4 mutations in MSS cancers, but by one or more indel receptor mutations (TGFBR2, ACVR2A, BMPR2 and ACVR1B) in MSI cancers." (PMID 39112709, 2024). "We found that the BMP4 ligand gene corresponding to receptor BMPR2 is expressed mainly in CAFs, and it has been demonstrated in other cancers types that BMPR2 is involved in cancer progression and is closely related to the EMT process." (PMID 36460803, 2023). "Our studies show that inhibition of BMPR2 destabilizes the microtubules leading to lysosome activation, which sensitizes cancer cells to LMP and cell death." (PMID 34563224, 2021). "Among the validated gene targets of both miR-194-5p and miR-374a-5p, we also found CCND2, AXIN2, and BMPR2, regulated by the Hippo signaling pathway, involved in stemness and cancer biology." (PMID 34828332, 2021). "Recent studies have shown that BMPR2 Smad-independent signaling regulates cell survival mechanisms in cancer cells." (PMID 34563224, 2021). "Our studies support that BMP survival mechanisms in cancer cells are mediated predominantly by BMPR2." (PMID 31744505, 2019). "After excluding the known miRNA-mRNA pair (hsa-miR-181a::BMPR2), 43 among 44 miRNA-mRNA pairs can accordingly be regarded as the putative novel multi-cancer-related miRNA-mRNA pairs." (PMID 28105958, 2016).
cancer (continued). "Core pathway analysis revealed that 4 of these 12 target genes - Bmi1, Birc4, Bmpr2 and Ptpn12 - have been found to be significantly deregulated in cancer." (PMID 21846369, 2011). "Displaying the dysregulation of BMPR2 and its effect on various cancer types." (PMID 40136410, 2025). "The present study examines whether the inhibition of BMPR2 destabilizes the microtubules in cancer cells and whether this effects survival." (PMID 34563224, 2021). "ITGB3 and BMPR2 genes were key regulators of cell migration and invasion of cancer cells." (PMID 32315343, 2020). "Recently, BMPR2 was reported with contradicting functions in cancers." (PMID 31889906, 2019). "Bone morphogenetic protein receptor 2 (BMPR2) has been identified in several types of cancer." (PMID 28938584, 2017). "The decreased presence or absence of BMPR2 is linked to a negative outlook in certain cancer types." (PMID 40136410, 2025). "KEGG pathway enrichment was performed on 74 target genes using DAVID, and four genes, BMPR2, HMOX1, HNRNPK and ZEB1, were enriched on the “microRNAs in cancer” signal pathway." (PMID 38693503, 2024). "Regarding the mechanism of this cancer-like vascular remodeling, TGF-β/Smad3, BMPR2 pathways, and O2-sensitive voltage-gated K + channels are believed to be the important pathways." (PMID 35002707, 2021). "Establishing the interaction between BMPR2 and BRCA1 strengthened the link between cancer and PAH; however, the findings need to be corroborated with a larger dataset." (PMID 33086628, 2020). "The mechanism responsible for the downregulation of BMPR2 in EBNA1-expressing and EBV-infected carcinoma cells in vitro is unclear, but the fact that these cells showed robust Smad1/5/8 phosphorylation suggests that ACVR2A or ACVR2B can substitute for BMPR2." (PMID 32708289, 2020). "XIAP inhibition of caspases promotes resistance to many cancer therapeutics including radiation, chemotherapeutics, and TRAIL The inhibition of BMPR2 decreases the expression of XIAP and inhibits the activity of TAK1." (PMID 31744505, 2019). "Despite studies linking neurological diseases to alterations in BMPR2 trafficking, mediated by the stabilization of the microtubules, the role of BMPR2 regulation of microtubules in cancer cells and its effect on survival has never been studied." (PMID 34563224, 2021). "Some studies showed that the induction of miR-135a expression in different types of cancers could suppress cell proliferation through target genes (c-MYC, STAT6, SMAD5, and BMPR2)." (PMID 34377051, 2021). "Recent studies have shown that bone morphogenetic protein receptor 2 (BMPR2) regulates cell survival signaling events in cancer cells independent of the BMP type 1 receptor (BMPR1) or the Smad-1/5 transcription factor." (PMID 34563224, 2021). "It is not known whether BMPR2 regulates the microtubules in cancer cells and what effect this has on cell survival." (PMID 34563224, 2021). "Furthermore, it is not known whether different cancer types have differences in trafficking of BMPR2 affecting its activity and/or response to BMPR2 inhibitors." (PMID 34563224, 2021). "JL5 only has weak inhibition of BMPR2 (IC50 8 μM) compared to its inhibition of the BMP type 1 receptors (5 nM), which may explain its lack of suppression of BMPR2 signaling in some cancer cells." (PMID 34563224, 2021).
connective tissue disease (7 papers, 2016 to 2024). "Our low frequency of BMPR2 variants is more in line with small studies on PH associated with connective tissue disease (CTD)." (PMID 36292254, 2022). "The first deceased patient had APAH (connective tissue disease) and he was carrier of c.251G > T (p.C84F) and c.981T > C (p.P327P) BMPR2 mutations." (PMID 27630060, 2016). "Although antinuclear antibodies were present in all adults with BMPR2 mutations, autoantibodies characteristic of a specific connective tissue disease were absent." (PMID 38541628, 2024).
infection (6 papers, 2007 to 2023). The state of being infected such as from the introduction of a foreign agent such as serum, vaccine, antigenic substance or organism. "Moreover, in vivo, we observed that infection significantly reduced Cav-1 and BMPR2 expression and promoted significant pulmonary vascular injury and remodeling." (PMID 37908354, 2023). "We examined the expression of hallmarks of BMP signaling during mycobacterial infection and found transcript levels of Bmp2, Bmp4, Bmpr2, and Id2 were consistently upregulated upon infection of mouse peritoneal macrophages with Mtb H37Ra as well as virulent Mtb H37Rv." (PMID 29449840, 2018). "We established that mycobacteria-activated BMP signaling required canonical receptors BMPR2 and BMPR1a, as overexpressed CA BMPR1a spurred an activation of BMP signaling, while a dominant-negative form of BMPR2 failed to activate the cascade even during infection." (PMID 29449840, 2018). "While cluster 7 showed a set of genes involved in cell cycle (P29, APBB2, GPS1) and the TGFβ-pathway (BMPR2, THBD) up-regulated 6 hours post infection, no concise network or significant functions/pathways could be identified." (PMID 18047719, 2007).
cardiovascular disease (4 papers, 2015 to 2023). "Currently, the involvement of epigenetic alteration or regulation of BMPR2 in PAH progression has not been clearly defined; however, there are several examples of the involvement of epigenetic regulation of BMPR2 in various pathological conditions including cardiovascular disorders." (PMID 26228095, 2015). "We predicted 6 candidate genes (PANK1, TRIB1, BMPR2, HDAC9, THBS1, and LARP1) that might bind to miR-942-5p and played a role in cardiovascular disease." (PMID 33869307, 2021).
vasculopathy (2 papers, 2013 to 2024). "BMPR2 loss-of-function mutations promote pro-proliferative signaling, resulting in characteristic PAH vasculopathy." (PMID 38731946, 2024). "The animals phenocopy patients with genetic mutations in BMPR2 leading to PAH but lack autoimmunity, microvascular vasculopathy, or fibrosis and thus should be considered a model of hereditary PAH but not SSc-PAH." (PMID 38731946, 2024).
musculoskeletal disorders (1 paper, 2025). "While BMPR2 is a well-known target of miR-125b in musculoskeletal disorders, RUNX2 is always described as an indirect target." (PMID 39897583, 2025).
neurological diseases (1 paper, 2021). "Mutations in BMPR2 trafficking proteins leads to overactive BMP signaling, which leads to neurological diseases caused by BMPR2 stabilization of the microtubules." (PMID 34563224, 2021).